RAD51C (RAD51 paralog C)
Diseases named in the same sentence as RAD51C in open-access papers (continued):
Sharing a sentence is not in itself a finding about the gene and the disease.
cancer (165 papers, 2012 to 2026). A tumor composed of atypical neoplastic, often pleomorphic cells that invade other tissues. "Two patients harbored additional pathogenic germline variants in cancer predisposition genes: 1 in RAD51C and 1 in PIK3CA." (PMID 41487701, 2026). "All five genes (BAP1, FANCA, RET, FH, and RAD51C) are well-known cancer predisposing genes with incomplete penetrance and variability of expression." (PMID 38700789, 2024). "We identified 6 patients of co-mutations in the CDK12 and RAD51C genes across various cancer types among 67,083 cancer patients in the cBioPortal database." (PMID 38953104, 2024). "The deletion is sandwiched between the FA/cancer patient-associated RAD51C amino acids R258H and G264S, corresponding to murine R267 and G273." (PMID 36906610, 2023). "An increased level of genomic instability and apoptosis was found in RAD51C-deficient cancer cells treated with Olaparib." (PMID 37508568, 2023). "RAD51C cancer mutations occur throughout the protein sequence, challenging prediction of functional impacts and implied pathogenicity." (PMID 37488098, 2023). "Comprehensive analyses of breast and ovarian cancer pedigrees and patients with Fanconi anemia, a rare disorder characterized by hematological and developmental defects, pinpointed RAD51C as a cancer predisposition gene." (PMID 37681281, 2023). "The analysis of other cancer genes in BU patients identified a carrier of a pathogenic germline variant in RAD51C." (PMID 36900320, 2023). "Combining exemplary homozygous hypomorphic Brca2/Fancd1 and Rad51c/Fanco mutations in mice phenocopies human FA with bone marrow failure, rapid death by cancer, cellular cancer-drug hypersensitivity and severe replication instability." (PMID 36906610, 2023). "The proportion of germline SV mutations in BRCA1 and BRCA2 was markedly elevated in OC (BRCA1, 3.4%; BRCA2, 1.7%) and PC (BRCA2, 2.2%) compared to other cancers, as was the proportion of germline SV mutations in the HR genes RAD51C and RAD51D in OC." (PMID 37821580, 2023). "Previous studies have found that RAD51C germline mutations are connected to cancer by preventing HR-mediated repair." (PMID 37508568, 2023). "The gene RAD51C is known for its function in DNA repair and its mutations have been implicated in various cancers." (PMID 34244761, 2022). "In the cohort of cancer-free women, only one individual carried a pathogenic variant, RAD51C:c.264_265insA." (PMID 35353237, 2022). "The RAD51C gene is highly expressed in ESCC cells, causing cancer progression, low survival, and increased tumor size via the p38/Akt pathway due to the activation of the RAD51C pathway through the single‐strand annealing (SSA) mechanism." (PMID 36147024, 2022). "RAD51C-deficient cancer cells are sensitive to the PARPI olaparib and undergo cell death by inducing G2/M cell cycle arrest and apoptosis." (PMID 35785170, 2022). "The presence of Signature 3 in cases with BRCA1, PALB2 and RAD51C variants, as well as tumor enrichment of these variants, suggest that these cancers are HR-deficient." (PMID 33917078, 2021). "The results presented here imply that cancer family history should be considered when counseling carriers with RAD51C or RAD51D pathogenic variants because it can lead to large differences in the cumulative TOC and BC and thus influence clinical management." (PMID 32107557, 2020). "Under this model, the risk of developing TOC or BC for RAD51C/D pathogenic variant differs by cancer family history." (PMID 32107557, 2020). "RAD51C deficiency accumulates somatic mutation, which leads to genomic instability, and finally promotes cancer." (PMID 33107155, 2020). "Cascade screening on maternal and paternal sides demonstrated that, despite the propensity toward maternal cancers, the RAD51C c.571 + 4A > G variant was inherited from the proband's father (PID: II‐6)." (PMID 31782267, 2020).
cancer (continued). "In summary, the recurrent RAD51C c.571 + 4A > G variant is associated with cancers that occur in two or more heterozygotes include BC, diagnosed in five females (age range: 37–77) and OC, diagnosed in four females (age range: 41–67)." (PMID 31782267, 2020). "For a specific example, SNU-601 was highly sensitive to olaparib due to RAD51C-deficiency, which was also identified in several cancer types." (PMID 32028591, 2020). "In summary, the RAD51C‐associated cancer in family 05011 is BC (age range: 37–77) and OC (age range: 41–67)." (PMID 31782267, 2020). "In this study, although other cancers were noted in the extended pedigrees, the extent to which the RAD51C c.571 + 4A > G variant underlies these various cancers requires further clinical recruitment and genotyping." (PMID 31782267, 2020). "The Cancer Genome Atlas reported that 7 of 287 gastric patients (2.4%) showed genetic alterations in RAD51C gene, and it has been well established that loss of RAD51C is associated with increased cancer risk." (PMID 32028591, 2020). "Whole‐exome sequencing identified 66 variants that passed filtering criteria (excluding RAD51C c.571 + 4A > G) with 16 variants associated with cancer, specifically with tumor progression only and were excluded from further investigation." (PMID 31782267, 2020). "While BRCA1 is the most recognized predisposing gene for BC and OC, RAD51C was first identified as a putative cancer-predisposing gene in BC/OC families in 2010." (PMID 32276467, 2020). "Although pathogenic variants have been identified in individuals with other cancer types, the phenotypic spectrum of RAD51C in cancer remains to be fully determined." (PMID 31782267, 2020). "Recently, the acquisition of PARPi-resistance has been investigated in BRCA1-deficient cancer cells, and has also been observed in RAD51C and RAD51D patients." (PMID 30551670, 2018). "Recently, RAD51C (RAD51 paralog C) gene has been identified as human cancer gene associated with higher risk for inherited breast and ovarian malignancies." (PMID 29143133, 2017). "In our study, only one proband, carrying the pathogenic RAD51C mutation, displayed family cancer history that included OC and BC cases." (PMID 26057125, 2015). "We observed several significant associations in specific cancer types: RAD51C in AML, ATM in PRAD and PALB2 in STAD." (PMID 26689913, 2015). "Although PVs in RAD51C/D genes have been clearly linked to Ovarian Cancer susceptibility and to ER-negative breast cancer risk, the association with other cancer types remains unclear." (PMID 40282418, 2025). "However, in the context of a second also seemingly benign Brca2 mutation, the added Rad51c NTDI mutation strongly drives cancer in these mice and confers cancer therapy sensitivity." (PMID 37488098, 2023). "On a similar note, cancers with the deficient HR genes RAD51C, RAD51D and PALB2 being treated with PARP inhibitors subjected to secondary mutations allowed for the induction of proper, or semi-proper, protein functioning, leading to a restoration of sufficient HR and PARPi resistance." (PMID 37508568, 2023). "Notably, the maternally transmitted NBN and the paternally transmitted RAD51C variants are rare in the gnomAD non-cancer population (MAF: 0.00003 and 0.005, respectively)." (PMID 33840814, 2021). "We propose this scenario as an underlying genetic mechanism in the siblings studied herein (Case-77/Case-78) in whom we detected VUSs in the DNA repair genes NBN and RAD51C, which might jointly lead to cancer susceptibility." (PMID 33840814, 2021). "In summary, the RAD51C‐associated cancer in family 22427 is OC (age 67)." (PMID 31782267, 2020). "It is evident that RAD51C pathogenic variants may be associated with other cancers as previously reviewed." (PMID 31782267, 2020). "In summary, the RAD51C‐associated cancer in family 7214 is OC (age 66)." (PMID 31782267, 2020).
cancer (continued). "However, the optimal interpretation of gene-panel testing results requires precise cancer risk estimates for pathogenic variants in RAD51C." (PMID 32107557, 2020). "RAD51C‐deficient cancer cells were more sensitive to olaparib than were RAD51C‐proficient cancer cells, and the silencing of RAD51C in olaparib‐resistant cell lines could enhance olaparib sensitivity." (PMID 30672100, 2019). "Notably, we observed several novel associations between specific cancer types and genes, including RAD51C in AML, ATM in PRAD, PALB2 and EME2 in STAD." (PMID 26689913, 2015). "Furthermore, recent large-scale sequencing studies of breast cancer, ovarian cancer and testicular cancer patients and their families identified Rad51C mutations associated with increased cancer risk." (PMID 24742710, 2014). "Full-length RAD51C knock-out is lethal in normal and cancer cells with some exceptions, and functional RAD51C variant testing so far relied on knockdown of the protein or variant overexpression in cells that have overcome RAD51C essentiality, which may have secondary effects." (PMID 37488098, 2023). "A failure of this repair pathway that could be expected in cancer patients carrying germline pathogenic mutations in RAD51C and RAD51D sensitizes cancer cells to PARP inhibitors; therefore, patients carrying germline RAD51C and RAD51D mutations may benefit from this therapy." (PMID 26057125, 2015). "The cancer specifically acquired APOBEC3-context pathogenic mutations in PIK3CA (E545K) and RAD51C (P21S)." (PMID 40379787, 2025). "Based on the familial histories reported by the consultants, seven CRCs followed by five PrCs were the most common cancer diagnoses in untested relatives among RAD51C-positive families." (PMID 40282418, 2025). "Other mutations responsible for the development of this cancer are germline mutations in the BRIP1, RAD51C, or RAD51D genes." (PMID 40429755, 2025). "In contrast, data on cancer risk for PALB2, RAD51C, and RAD51D GPV carriers are limited and lifetime cancer risks largely depend on both family history and personal risk factors, such as age of menarche, use of oral contraceptives, and the number of children." (PMID 40428378, 2025). "Materials and Methods: Families harbouring PVs in RAD50, RAD51C, RAD51D, and BRIP1 were identified by analysing a cancer-predisposing genes panel using Ion S5 system technology." (PMID 40282418, 2025). "Altogether, these observations point to different roles for BRCA1 and RAD51C methylation in cancer development, progression and therapeutic potential." (PMID 39055334, 2024). "Our findings indicate that high-level tumour methylation of BRCA1 and RAD51C should be explored as a PARP inhibitor biomarker across multiple cancers." (PMID 39055334, 2024). "Knowledge about RAD51C and RAD51D mutations is important for identifying individuals at increased risk of cancer for early detection and screening." (PMID 39202057, 2024). "It is well established that cancer risk is modified by family history (BRCA1/2; PALB2; RAD51C and RAD51D (RAD51C/D))." (PMID 38443545, 2024). "Promoter-associated DNA CpG methylation has been reported in cancer for some HRR genes, specifically, BRCA1 and RAD51C." (PMID 39055334, 2024). "RAD51C methylation was observed more broadly across cancer types, especially in those characterised by the distinctive CpG island methylator phenotype, CIMP." (PMID 39055334, 2024). "Analysing selected promoter probes of BRCA1 and RAD51C, we identified promoter methylation of BRCA1 (meBRCA1) or RAD51C (meRAD51C) in 15 out of 23 cancer types." (PMID 39055334, 2024).
cancer (continued). "When delayed from age 45 years to 50 years, RRSO yielded fewer QALYs and cancers prevented despite slightly larger NMB for RAD51C, RAD51D, and BRIP1 PV carriers." (PMID 38334999, 2024). "Here, we report 9 out of 24 patients with non-contributory family history, harboring germline heterozygous deleterious mutation in well-known cancer predisposing genes (CHEK2, RAD51C, BRCA2, FANCA, RET, FH, and BAP1)." (PMID 38700789, 2024). "Overall, 15 patients out of 521 (2.9%) showed PVs and LPVs in five cancer-predisposing genes other than BRCA1/2 (PALB2, CHEK2, ATM, RAD51C, and RAD51D)." (PMID 37628581, 2023). "PARPi activity was also demonstrated for BRCAwt cancers due to mutations in genes critical for DNA repair (e.g., ATM, BARD1, BRIP1, CHEK2, NBN, PALB2, RAD51C, and RAD51D)." (PMID 36910637, 2023). "Guided by cancer patient variants and the CX3 structure, we define a CTDI region on RAD51C important for fork protection and ATP binding." (PMID 37488098, 2023). "FA displays an autosomal recessive inheritance, but cancer risk is associated with some heterozygous mutations in the following genes: BRCA2 (FANCD1), BRIP1 (FANCJ), PALB2 (FANCN), RAD51C (FANCO), BRCA1 (FANCS)." (PMID 37239385, 2023). "Several PARP1 inhibitors have been FDA-approved for the treatment of DNA damage repair (DDR)-deficient cancers including those harboring BRCA1/2, ATM, and RAD51C mutations." (PMID 37821462, 2023). "By contrast, silencing of RAD51C in resistant cancer cell lines increases the sensitivity to olaparib and decreases RAD51 foci." (PMID 35785170, 2022). "For each patient, we also showed the risk in the well-known high-penetrance cancer risk alleles BRCA1 and BRCA2 with respect to other moderate-penetrance alleles including PALB2, CHEK2, ATM, BARD1, RAD51D, RAD51C and BRIP1." (PMID 35886069, 2022). "Indeed, another OC case harbouring this RAD51C variant was identified in a woman diagnosed with a HGSC of unknown origin (likely upper genital tract) in a hereditary cancer clinic by medical genetic panel testing and was provided to us at the conclusion of this study." (PMID 35565380, 2022). "To assess the importance of promoter methylation in the evaluation of HRD classifiers' performance, we removed the methylation data of BRCA1/RAD51C promoters in breast and ovarian the only cancer types for which methylation data were available." (PMID 35783256, 2022). "Genetic variants of unclear significance were however detected in genes such as CDH1, DICER1, MEN1, RET, CREBBP, RAD51C, or SOS1, which are linked to autosomal dominant predisposition to cancer." (PMID 35250968, 2022). "Pathogenic variants in BRCA2/FANCD1, PALB2/FANCN, BRIP1/FANCJ, and RAD51C/FANCO have known adult-onset cancer risks, and there are recommendations for carriers to have increased cancer surveillance, consider chemoprevention, or undergo preventative surgeries." (PMID 35359366, 2022). "Several cancer-associated genes have been identified on chromosome 17q, including PPM1D, EME1, BRCA1, ERBB2, NF1, RAD51C, BRIP1 and BIRC5." (PMID 34885154, 2021). "Genes that are essential in eHAP cells include cancer risk genes such as PALB2, BARD1, RAD51C, and RAD51D, which have thousands of variants recorded in ClinVar." (PMID 33691754, 2021). "But the most remarkable pro-cancer RAD52 phenotype is seen in cancer cells deficient in any of the following DNA repair proteins: BRCA1, BRCA2, PALB2, XAB2 or RAD51 paralogs: RAD51B, RAD51C, RAD51D, XRCC2 and XRCC3." (PMID 34887904, 2021). "In contrast to RAD51C and RAD51D, XRCC2, XRCC3 and RAD51B variants are less frequently observed in tumors and the cancer risk for individuals harboring these variants remains controversial." (PMID 33015624, 2020).
cancer (continued). "These estimates will facilitate the genetic counseling of RAD51C and RAD51D pathogenic variant carriers and justify the incorporation of RAD51C and RAD51D into cancer risk prediction models." (PMID 32107557, 2020). "Family members of patients with FA who are heterozygous carriers of PV in genes from the fourth module FANCD1 (BRCA2), FANCJ (BRIP1), FANCN (PALB2), FANCO (RAD51C) and FANCS (BRCA1) are at increased risk to develop cancer." (PMID 33371494, 2020). "Here, we use a large collection of families with RAD51C and/or RAD51D pathogenic variants to estimate age-specific TOC and BC risks and assess how these vary by family history of cancer." (PMID 32107557, 2020). "In contrast to this, monoallelic variants of the RAD51 gene and of five of its paralogs have recently been involved in cancer predisposition: RAD51B, RAD51C, and RAD51D in OC; RAD51, RAD51B, and XRCC2 in BC." (PMID 32046255, 2020). "There is a male (II‐3) and a female (II‐7) who carry RAD51C c.571 + 4A > G and are cancer‐free at ages 76 and 62 respectively." (PMID 31782267, 2020). "While biallelic mutations in one of the FA genes can give rise to FA, heterozygous mutations in many of these same genes, including RAD51C and BRCA2, result in cancer predisposition." (PMID 33015624, 2020). "Secondary mutations across various cancer types were discovered to cause the reversion of DDR protein or gene function, such as BRCA1/2, PALB2, and RAD51C/D, resulting in the restoration of HR repair function and nullifying synthetic lethality." (PMID 32883316, 2020). "RAD51C was found to be densely methylated in both cancer cell lines and tumour tissue samples, resulting in low RAD51C expression." (PMID 30672100, 2019). "Previous reports have also established that other promoters, such as the AFP, Rad51C, human telomerase reverse transcriptase (hTERT), and midkine promoters, are expressed in a majority of human cancers." (PMID 26498690, 2015). "The association of ‘early’ FA genes with FANCD2 monoubiquitination defects with increased cancer susceptibility is much weaker compared with the ‘late’ FA genes such as BRCA1, BRCA2, BRIP1, PALB2 and RAD51C." (PMID 26085575, 2015). "To further confirm that Rad51C is overexpressed in cancer cells we examined the protein levels by Western blot." (PMID 24742710, 2014). "We demonstrated that Rad51C promoter can be used to transcptionally target cancer cells and identified a 2 kb promoter fragment that provides strong differential expression in cancer cells." (PMID 24742710, 2014). "The activity of Rad51C promoter fused to a reporter gene was dramatically higher in cancer cells relative to the increase in the endogenous levels of Rad51C transcript." (PMID 24742710, 2014). "To identify cancer-specific promoters we first compared the expression levels of Rad51B, Rad51C, Rad51D and Rad52 in a panel of seven normal and seven cancerous cells lines." (PMID 24742710, 2014). "A construct containing Rad51C promoter driving diphtheria toxin A efficiently killed several types of cancer cells with very mild effect to normal cells." (PMID 24742710, 2014). "In order to identify alternative promoters with high specificity to cancer cells we examined the tumor specificity of Rad51 paralogs Rad51B, Rad51C, Rad51D and Rad52." (PMID 24742710, 2014). "Here, we explored the utility of the HR gene Rad51B, Rad51C, Rad51D and Rad52 for transcriptionally targeted therapy of cancer." (PMID 24742710, 2014).